BDNF (brain derived neurotrophic factor)
Diseases named in the same sentence as BDNF in open-access papers (continued):
Sharing a sentence is not in itself a finding about the gene and the disease.
Obesity (continued). "Considering the mechanisms of action of BDNF and the multitude of factors influencing the secretion of this protein in healthy people, in obesity, and under the influence of physical exercise, it is important for the authors of future studies to prepare detailed descriptions of experimental studies." (PMID 38785805, 2024). "Therefore, further research is needed to understand the mechanisms of exercise and BDNF regulation to develop more effective therapies for obesity and optimize exercise-based treatments." (PMID 38785805, 2024). "The principal objective was to discern whether acute exercise or a more regular physical exercise could elicit alterations in circulating BDNF levels in comparison to a control group within the context of obesity." (PMID 38785805, 2024). "Likewise, another study notified that acute high-intensity exercise (20 min at 85% of VO2max) triggered a rise in serum BDNF levels in inactive adult patients with obesity." (PMID 38785805, 2024). "Mice with mutations in these two promoters developed obesity, but mice with mutations in promoter IV or promoter VI did not, suggesting that the first cluster of BDNF is involved in energy homeostasis." (PMID 37238691, 2023). "Nevertheless, effects of some SNPs appear to be more pronounced in children and diminish later in life as has been shown for the associations of variants in TMEM18, GNDPA2, MC4R, NEGR1, BDNF and KTCD15 with early-onset obesity, and particularly for INSIG2 variants." (PMID 37819541, 2023). "Alongside NGF and BDNF alterations, hyperleptinemia and an increased number of mast cells in subcutaneous abdominal adipose tissue are also reported, shedding light on the role of these metabotrophins in the pathogenesis of obesity and related diseases." (PMID 38026693, 2023). "However, it's important to note that the relationship between BDNF and obesity is complex and not fully understood." (PMID 37120612, 2023). "Another study that examined the relationship between overweight/obesity and executive control (EC) in young adults and further analyzed the mediating effect of neurotrophic factor (BDNF) showed that overweight or obesity is related to lower BDNF levels, which in turn is related to lower EC." (PMID 36831706, 2023). "However, the molecular mechanism of QA in the regulation of synaptic ultrastructure and BDNF expression requires further elucidation in obesity." (PMID 36787221, 2023). "Our data also indicate that BDNF-producing cells are only partially responsible for obesity in SMS: male and female cKO mice become overweight by 15 wk, in contrast to SMS mice which become obese by 9 wk of age, suggesting that non-BDNF neurons contribute to SMS phenotypes." (PMID 37956053, 2023). "Shiikuwasha extract has anti-obesity effects and alleviates skeletal muscle atrophy and osteoarthritis progression, however, it is unknown whether Shiikuwasha affects BDNF production." (PMID 38082356, 2023). "Furthermore, BDNF levels at 1 year after anti-obesity treatments were comparable to baseline levels." (PMID 37436597, 2023). "Our findings indicate that drop-set resistance exercise interventions can increase NGF and BDNF levels in middle-aged Korean women with obesity, which may have significant clinical implications for enhancing cognitive function and mood regulation." (PMID 37176576, 2023). "However, in a mouse model of obesity, 4 weeks of low-dose Zn supplementation (15 ppm) reversed proliferation, neuronal differentiation, and BDNF levels." (PMID 36602746, 2023). "Because GABAergic Rai1 loss did not induce obesity and most BDNF-producing neurons are glutamatergic." (PMID 37956053, 2023). "Similarly to obesity, there are several other conditions in pediatric and adolescent populations, in which increased BDNF concentrations have been reported in comparison with healthy controls." (PMID 37548699, 2023).
Obesity (continued). "Dysregulated BDNF-TrkB signaling has been implicated in both ASD and in obesity, with dysfunction of the hypothalamus being critical in obesity, but the changes in signaling mediators downstream of hypothalamic TrkB in BTBR mice have not been studied sufficiently." (PMID 36893171, 2023). "The aim of this study was to assess the possible differences in the obesity-related and glucose metabolism parameters between some BDNF genotypes’, that may depend on the daily energy and macronutrients intake." (PMID 37085692, 2023). "Studies on the physiology of BDNF may explain the link between obesity, MetS and neurodegenerative disorders, as well as the potential for early prevention, diagnosis, and novel treatments." (PMID 37548699, 2023). "Lastly, the hypothesis concerning the compensatory upregulation of BDNF in adolescents with obesity and MetS needs to be further explored, and examined in other early disruptive processes that carry on to adulthood." (PMID 37548699, 2023). "Increasing the number of studies showing cut-off points for obesity for both asprosin and BDNF may contribute to understanding obesity pathology." (PMID 37120612, 2023). "In this study, our results showed a significant negative association between BDNF protein concentrations and BMI as a measure of obesity." (PMID 36676721, 2022). "Elevated BDNF levels have been shown in populations with obesity or metabolic syndrome." (PMID 36138878, 2022). "Based on previous studies, it seems that alteration in BDNF levels as a result of alteration in gut microbiota caused by TRF may be a novel strategy for management of food addiction and obesity." (PMID 35689257, 2022). "HFD and obesity also induce downregulation of BDNF in the hippocampus and cortex of rodents." (PMID 35761012, 2022). "BDNF is able to suppress appetite signals in the brain and prevent obesity." (PMID 35739547, 2022). "Most BDNF studies on obesity have been conducted in animal models with limited human studies." (PMID 36676721, 2022). "Thus, we evaluated the effect of CAF on synaptophysin and BDNF as markers of neuroplasticity to further investigate the relationship between gut and brain in obesity." (PMID 36235574, 2022). "Taken together, our results revealed that all high dietary fatty acid diets induced obesity accompanied by lipid disorders, intestinal barrier dysfunction, and changes in secreted cytokines from gut-brain axis including BDNF, 5-HT, leptin, insulin, and ghrelin." (PMID 35739547, 2022). "Our ELISA test results for BDNF protein in the serum showed that the association between BDNF protein concentrations and BMI as a measure of obesity has a significantly negative correlation." (PMID 36676721, 2022). "In addition, the brain-derived neurotrophic factor (BDNF) as well as its neurotrophic receptor kinase 2 (NTRK2) receptor are also strongly expressed in the VMN, and the deletion of BDNF and its receptor leads to hyperphagia and obesity in humans and mice." (PMID 35721722, 2022). "Based on previous studies, gut microbiota may play an important role in regulating obesity, energy balance, and also the host eating behavior through affecting appetite and hormone levels such as BDNF." (PMID 35689257, 2022). "Furthermore, we conducted a post hoc test using the Dunn–Bonferroni approach; the results indicated that BDNF levels were significantly lower in obesity classes II and III than the normal weight (p < 0.05)." (PMID 36676721, 2022). "Additionally, the results obtained from unadjusted linear regression analysis to examine the correlation between variables BDNF and β-NGF levels showed a positive association with obesity measures such as BMI z-score, WC z-score, and WHtR z-score." (PMID 35626286, 2022). "Furthermore, there were significantly lower BDNF levels in obesity classes II and III than in the normal weight control group (p < 0.05)." (PMID 36676721, 2022).
Obesity (continued). "Among central nervous system (CNS) determinants of obesity, BDNF could exert a potentially significant role." (PMID 35911513, 2022). "In addition to developmental events, BDNF has a role in synaptic plasticity, obesity, addiction, and many neuropsychiatric disorders." (PMID 35721318, 2022). "While a full functional loss of one BDNF allele seems to cause severe obesity in humans, there is no consistent evidence about the pathogenic variants of this gene." (PMID 36452324, 2022). "The salivary concentration of BDNF and NGF was higher in obese children, and it is positively associated with anthropometric measures, suggesting that neurotrophins can be used as a non-invasive predictor of obesity-related complications in children." (PMID 35626286, 2022). "Visceral and subcutaneous LECs displayed an obesity-associated upregulation of the RAGE pathway, integrins and ECM–receptor interactions, while a downregulation in the brain-derived neurotrophic factor (BDNF), interleukin-5 (IL-5), IL-2 and AP1 networks was observed." (PMID 36400935, 2022). "Via the hypothalamic melatonin pathway, BDNF can regulate metabolism and may protect against obesity." (PMID 35408868, 2022). "We hypothesized that lower serum BDNF levels are related to elevated BMI and obesity in Saudi Arabia." (PMID 36676721, 2022). "As a result, BDNF deficiency leads to the development of obesity because the person would not have any feeling of fullness." (PMID 36676721, 2022). "The obesity panel revealed BDNF was increased while both leptin and glucagon were reduced." (PMID 35574470, 2022). "Their variants affect the obesity risk by modulating the binding affinity of obesity-related transcription factors, such as STAT3, CEBPB, TCF7L2, FTO, and GATA2, and changing the phosphorylation of proteins, such as BDNF with the rs6265 risk allele." (PMID 34836030, 2021). "Finally, the multiple intermediary models in SPSS were used to analyze the mediating effect of 5-HT and BDNF between overweight/obesity and EC." (PMID 33916706, 2021). "The results obtained in this study indicated that 5-HT and BDNF were significant mediators in the link between overweight/obesity and EC, which validated our hypothesis." (PMID 33916706, 2021). "The findings from the present study provide no consistent statistically significant evidence for an association of the five investigated obesity-associated genes (FTO, TMEM18, MC4R, SEC16B, and BDNF) with baseline anthropometric traits or their changes after 12 months of behavioural intervention." (PMID 33801339, 2021). "Based on the available scientific evidence, we proposed the second hypotheses: BDNF can be used as an intermediary variable for the effect of overweight/obesity on EC." (PMID 33916706, 2021). "Taken together, these findings only support that the elevated expression of BDNF in VMH may be beneficial for ameliorating obesity." (PMID 33868169, 2021). "However, an interaction of endothelial function and OSA on BDNF levels was found in this pediatric population with obesity." (PMID 35127775, 2021). "Altogether, these data highlight a role of BDNF in hedonic eating and in obesity." (PMID 33367955, 2021). "Moreover, in the general population from newborns, adults to ages, studies have reported that BDNF gene is correlated with energy, carbohydrate intake, physical activities, behavioral characteristics, BMI, and obesity." (PMID 34482368, 2021). "Recently, increasing attention has been focused on the biological pathway between the overweight/obesity on EC and, as biogenic regulator factors, serotonin (5-hydroxytryptamine (5-HT)) and brain-derived neurotrophic factor (BDNF) have been studied extensively." (PMID 33916706, 2021). "The expression of low levels of BDNF in the nervous system may trigger energy homeostasis, thereby developing obesity and glucose intolerance, and metabolic disorders." (PMID 34054732, 2021).
Obesity (continued). "Animal models have shown that the deletion of BDNF in the mouse brain results in obesity, hyperphagia, and impaired locomotor activity, and in humans the loss of one copy of the BDNF gene is also associated with hyperphagia, severe obesity, and impaired cognitive function." (PMID 34867148, 2021). "A GWAS study in Danish, Icelandic, Dutch, European Americans, and African American adults has shown that SNPs in the FTO, MC4R, BDNF, and SH2B1 genes are highly associated with obesity risk via modulating leptin secretion to induce leptin resistance in different ethnicities." (PMID 34836030, 2021). "The present findings implicate that BDNF levels in patients suffering from obesity might be involved in food craving and obesity in humans." (PMID 33367955, 2021). "The reported findings implicate that in a physiological and healthy system BDNF might operate by reducing cue-reactivity, which again might prevent craving for food, overeating and obesity." (PMID 33367955, 2021). "Nevertheless, to what degree BDNF activity may contribute to the obesity-related side effects of APDs is uncertain." (PMID 35047549, 2021). "Our results, therefore, could be taken to indicate that overweight/obesity-related 5-HT and BDNF may be one biological pathway underpinning links between overweight/obesity and EC." (PMID 33916706, 2021). "Based on the available scientific evidence, we proposed the final hypotheses: Both 5-HT and BDNF are used as intermediary variables for the effect of overweight/obesity on EC to construct a multiple intermediary mode." (PMID 33916706, 2021). "Since BDNF and S100B protein are involved in both FM and obesity, it is reasonable to hypothesize an interplay among these biomarkers as far as brain plasticity is concerned, in the modulation of eating behavior in FM." (PMID 34591410, 2021). "This indicated that overweight/obesity could directly predict the EC and also through BDNF’s mediating effect with 5-HT." (PMID 33916706, 2021). "It is indicated that 5-HT and BDNF might be the biological pathways underpinning the link between overweight/obesity and executive control." (PMID 33916706, 2021). "BDNF is also involved in regulating metabolic functions, such as fat oxidation and glucose utilization, and has been shown to be downregulated in those with obesity and type 2 diabetes." (PMID 34867148, 2021). "Further studies are needed to clarify the mechanism, and BDNF may be the effective intervention targets of severe obesity after smoking cessation." (PMID 34525971, 2021). "Similarly, in this study, the BDNF levels of college students played a partial mediating role between overweight/obesity and EC." (PMID 33916706, 2021). "In cohort stratified analyses, log-transformed BDNF was significantly associated with log-transformed hs-CRP and BMI in the CP cohort, suggesting that BDNF is associated with the observed inflammation and obesity in CP." (PMID 33497355, 2021). "Based on its widespread expression in hypothalamus (the center of appetite), researchers have proposed a hypothesis that BDNF and its tyrosine kinase receptor may be closely related to eating behaviors and energy balance, and further affect obesity." (PMID 34482368, 2021). "This study comparatively examined carriers and non-carriers of the BDNF Val66Met polymorphism on body composition, energy intake, and cardiometabolic profile among adolescents with obesity." (PMID 34867148, 2021). "The activation of BDNF-TrkB system can be a link in the development of hyperalgesia, obesity, and inflammation in painful form of diabetic polyneuropathy, and this connection is most likely made by phosphatidylinositol-3 kinase/Akt (PI3K/Akt) signaling pathway." (PMID 34586159, 2021). "Future studies will also consider the intermediary role that 5-HT and BDNF may play between the EC and overweight/obesity." (PMID 33916706, 2021).
Obesity (continued). "Therefore, this is the first study that examines the relationship between OSA, endothelial function and BDNF in a pediatric population with obesity." (PMID 35127775, 2021). "However, there were insignificant differences in overweight/obesity (p > 0.05, Cohen’s d = 0.22), EC (p > 0.05, Cohen’s d = −0.10), BDNF (p > 0.05, Cohen’s d = −0.20), and 5-HT (p > 0.05, Cohen’s d = 0.15) between the two genders." (PMID 33916706, 2021). "While the role of BDNF deletion in obesity and other metabolic characteristics has been explored, it is also possible that the PAX6 deletion may contribute to some of the metabolic abnormalities that can affect patients with WAGR Spectrum." (PMID 34970513, 2021). "Therefore, the current study has been undertaken to compute the GRS based on five obesity-linked key loci including MC4R rs17782313, BDNF rs6265, FTO rs1421085, TMEM18 rs7561317, and NEGR1 rs2815752 in this at-risk and under-represented population." (PMID 33859285, 2021). "Our results strengthen the rationale to develop treatments addressing the BDNF pathways to enrich the current multi-modal anti-obesity treatment options taking into account the partly redundant and complex mechanisms underlying the regulation of energy intake and expenditure." (PMID 33367955, 2021). "In this study, we hypothesized that the related 5-HT and BDNF levels play an intermediary role in the influence of overweight/obesity on EC." (PMID 33916706, 2021). "Indeed, preclinical studies have revealed that the BDNF signaling pathway is involved in the control of food intake, activity, resting metabolism rate, body weight, and obesity." (PMID 34482368, 2021). "BDNF is involved in the pathogenesis of obesity, type 2 diabetes mellitus, and metabolic syndrome." (PMID 32408716, 2020). "WAGR syndrome is a contiguous gene deletion syndrome on chromosome 11p13 characterized by Wilms’ tumour, Aniridia, Genitourinary anomalies and Mental retardation, with obesity present in patients with larger deletions encompassing BDNF along with the other critical genes (WAGRO syndrome)." (PMID 30926952, 2020). "However, genes associated with obesity have been also described to be associated with HD, such as POMC, NPY, CART, and BDNF." (PMID 32982666, 2020). "Rodent models provide robust evidence for reduced BDNF in obesity." (PMID 33013465, 2020). "In this perspective, the functional role of SST via activation of different SSTR subtypes in the modulation of BDNF and regulation of obesity is well supported by the regulation of hypothalamic–pituitary–adrenal axis (HPA) in presence of BDNF, CRH, and glucocorticoids (GCs)." (PMID 32272767, 2020). "Therefore, the purpose of this report was to examine the effect of KME ingestion before an OGTT on plasma BDNF in normal-weight (NW) adults and adults with obesity (OB)." (PMID 33013465, 2020). "However, our data showed that circulating mature-BDNF levels were inconsistent according to obesity status of the study women." (PMID 33375318, 2020). "BDNF is critically involved in hippocampal injury in the context of obesity/HFD." (PMID 32408716, 2020). "Based on evidence that serum BDNF levels were lower in patients with type 2 diabetes and obesity, one can speculate that serum BDNF levels increased as Taekwondo training alleviated obesity in overweight and obese adolescents." (PMID 32268592, 2020). "The relationship between BDNF and obesity in humans is less clear." (PMID 33013465, 2020). "Mutations in genes coding for SIM1, BDNF, and TRKB appear to be involved in the development of obesity in both mice and humans, although the regulatory mechanisms are still unknown." (PMID 33261141, 2020). "Therefore, it is important to verify the effects of behavior and pharmacological interventions for improving obesity on both, brain BDNF and inflammation levels." (PMID 32681810, 2020). "BDNF and FGF21 have been implicated in the pathogenesis of obesity, T2DM, and metabolic diseases." (PMID 32210348, 2020).